HACL1 (2-hydroxyacyl-CoA lyase 1)
Description:
Peroxisomal 2-OH acyl-CoA lyase involved in the cleavage (C1 removal) reaction in the fatty acid alpha-oxydation in a thiamine pyrophosphate (TPP)-dependent manner. Involved in the degradation of 3-methyl-branched fatty acids like phytanic acid and the shortening of 2-hydroxy long-chain fatty acids. Plays a significant role in the biosynthesis of heptadecanal in the liver (By similarity).
Synonyms: 2-HPCL; HPCL; HPCL2; PHYH2
Tractability: PROTAC: ubiquitination databases record sites on it; its protein half-life has been measured.
Gene: Protein-coding gene on chromosome 3 (15,560,582 to 15,601,883, reverse strand). Ensembl gene ENSG00000131373.
Subcellular location: Peroxisome
Subcellular location (Human Protein Atlas): Vesicles; Nucleoplasm
Pathways (Reactome):
Metabolism: Alpha-oxidation of phytanate
Protein localization: Peroxisomal protein import
Gene Ontology:
Molecular function: 2-hydroxyacyl-CoA lyase activity; 2-hydroxyphytanoyl-CoA lyase activity; ATP binding; carbon-carbon lyase activity; identical protein binding; magnesium ion binding; protein binding; thiamine pyrophosphate binding; catalytic activity; lyase activity
Biological process: fatty acid alpha-oxidation; fatty acid metabolic process; methyl-branched fatty acid metabolic process; phytanic acid metabolic process; protein targeting to peroxisome
Cellular component: peroxisome; cytosol; peroxisomal matrix
Genetic constraint (gnomAD): Loss-of-function variants: 12 observed, 11.05 expected, observed/expected ratio (o/e) 1.09, 90% interval 0.69 to 1.71. The upper end of that interval is the gene's LOEUF score, 1.71, which puts it in group 6 of 6, group 1 being the genes least tolerant of losing a copy. Missense variants: 167 observed, 162.93 expected, observed/expected ratio (o/e) 1.02, 90% interval 0.9 to 1.16. Synonymous variants: 49 observed, 59.98 expected, observed/expected ratio (o/e) 0.82, 90% interval 0.65 to 1.04.
Homologues: Orthologues: chimpanzee HACL1 (99% identical), macaque HACL1 (94% identical), rabbit HACL1 (89% identical), mouse Hacl1 (88% identical), pig HACL1 (88% identical), guinea pig HACL1 (86% identical), rat Hacl1 (85% identical), tropical clawed frog hacl1 (70% identical), zebrafish hacl1 (64% identical), Drosophila melanogaster Hacl (52% identical), Caenorhabditis elegans hacl-1 (48% identical). Paralogues in human: HACL2 (27% identical).
Diseases named in the same sentence as HACL1 in open-access papers:
HACL1 is named in the same sentence as 16 diseases in open-access papers, as found by Europe PMC text mining. Sharing a sentence is not in itself a finding about the gene and the disease. The quoted sentences say what the papers report.
Thiamine deficiency (2 papers, 2017 to 2019). Thiamine deficiency is a condition that occurs due to not enough thiamine (vitamin B1). "Given that both HACL1 and HACL2 are dependent on thiamine-pyrophosphate, one could expect an effect of thiamine deficiency on odd-chain fatty acids, but thiamine deficiency is currently very rare in Western countries." (PMID 29027957, 2017).
Ataxia (1 paper, 2022). Ataxia refers to impaired coordination of voluntary muscle movement. "Hacl1 deficient mice do not present with a severe phenotype, unlike mice deficient in other α-oxidation enzymes such as phytanoyl-CoA hydroxylase deficiency (Refsum disease) in which neuropathy and ataxia are present." (PMID 35055171, 2022).
breast carcinoma (1 paper, 2025). "For TGFB2-dependent biomarkers, elevated TGFB2 mRNA expression is a prognostic biomarker associated with breast cancer patients that is correlated with improved OS outcomes at high expression levels of GDAP1, TBL1XR1, RNFT1, HACL1, SLC27A2, NLE1, and TXNDC16." (PMID 41373732, 2025). "In cases dependent on TGFB2, increased mRNA expression of TGFB2 alongside higher levels of GDAP1, TBL1XR1, RNFT1, HACL1, SLC27A2, NLE1, or TXNDC16 was correlated with improved OS among breast cancer patients, of which four genes were upregulated in tumor tissues (SLC27A2, TXNDC16, TBL1XR1, GDAP1)." (PMID 41373732, 2025).
cholestasis (1 paper, 2021). Impairment of the bile flow caused by obstruction within the liver, or outside the liver in the bile duct system. "We speculate that HACL1 may be involved in cholestasis through the PPAR-α related signaling pathway, and it may be the gene target of SHCZF." (PMID 34512777, 2021). "By sequencing and bioinformatics analysis, CYP4A1, HACL1, F11R, and DBI were identified as possible pharmacodynamic gene targets of SHCZF in treating cholestasis rats." (PMID 34512777, 2021).
diabetes (1 paper, 2018). "Either way, 2-hydroxyacyl-CoA lyase 1, along with glyoxalase domain-containing protein 4 have been superficially studied and so far, their relationship with diabetes or obesity is not clear." (PMID 29857581, 2018).
Intellectual disability (1 paper, 2022). "So far, there has been no definite report of a HACL1 deficient patient, although HACL1 was one of 57 candidate genes for a recessive syndrome involving intellectual disability, muscle weakness and a characteristic face." (PMID 35055171, 2022).
nasopharyngeal carcinoma (1 paper, 2022). A carcinoma arising from the nasopharyngeal epithelium. "HACL1 is closely related to small-cell lung cancer, and ERICH3 may be a key biomarker in nasopharyngeal carcinoma." (PMID 35252170, 2022).
HACL1 also shares sentences with these, for which no sentence is quoted: breast adenocarcinoma (1 paper); iron deficiency (1); kidney adenocarcinoma (1); liver cancer (1); neuropathy (1); Obesity (1); Refsum disease (1); small cell lung carcinoma (1); tumor (1).